ITGA9 (integrin subunit alpha 9)
Diseases named in the same sentence as ITGA9 in open-access papers (continued):
Sharing a sentence is not in itself a finding about the gene and the disease.
mastitis (1 paper, 2024). Inflammation of breast tissue during lactation or postpartum due to an obstructed duct or infection. "ITGA9 is associated with mastitis in cows due to Protothera infection and affects milk quality." (PMID 38890842, 2024).
myeloma (1 paper, 2020). "Myeloma patients with low ITGA9 expression had more tendency of having the higher number of malignant PCs in BM and becoming the higher GEP group." (PMID 32581652, 2020). "In conclusion, ITGA9 was a vital cell adhesion molecule in myeloma which may be negtive regulated by MYC." (PMID 32581652, 2020). "GSEA results showed that ITGA9 was a vital cell adhesion molecule and may be repressed by MYC in myeloma." (PMID 32581652, 2020). "However, there is rare research on the role which ITGA9 and LAMB1 play in myeloma development and metastasis." (PMID 32581652, 2020).
neuropathy (1 paper, 2022). A disorder affecting the nervous system that manifests with pain, tingling, numbness, and/or muscle weakness. "It remains unknown how XCR1 and ITGA9 are involved in nociceptive transmission; however, their role seems to be extremely important in neuropathy, as our previous research proved the strong pronociceptive properties of their ligand, XCL1, in naive animals." (PMID 36618360, 2022). "These are particularly significant results since they indicate for the first time that ITGA9 may be an important potential target for the pharmacotherapy of neuropathy." (PMID 36618360, 2022). "Therefore, our results are particularly important because ITGA9 is not a typical chemokine receptor, which indicates the complexity of neuroimmunological processes occurring in neuropathy." (PMID 36618360, 2022).
Pleural effusion (1 paper, 2023). The presence of an excessive amount of fluid in the pleural cavity. "We identified three heterozygous ITGA9 missense VOUS in CSFE with pleural effusions that fall outside the protein domain described to be associated with disease." (PMID 36959127, 2023).
RASopathy (1 paper, 2023). Developmental syndromes caused by germline mutations (or in rare cases by somatic mosaicism) in genes that alter the Ras subfamily and mitogen-activated protein kinases that control signal transduction. "We describe novel variants in several LA genes, including a likely pathogenic variant in PIEZO1, and VOUS in PIEZO1, ITGA9, CELSR1, EPHB4, and TIE1, as well as novel VOUS in RASopathy genes." (PMID 36959127, 2023).
renal carcinoma (1 paper, 2024). A carcinoma arising from the epithelium of the renal parenchyma or the renal pelvis. "The results of immunohistochemical analysis indicate that the expression levels of COL9A3, GPC4, and ITGA6 in renal cancer tissue are higher than those in normal tissue, whereas the expression levels of FREM2, ITGA9, and P3HI are lower than in normal tissue." (PMID 38365923, 2024).
renal fibrosis (1 paper, 2020). A final common manifestation of a wide variety of chronic kidney diseases characterized by glomerulosclerosis and tubulointerstitial fibrosis. "Therefore, we assumed that melatonin treatment could suppress ITGA9 expression and, thus, inhibit renal fibrosis." (PMID 32727098, 2020).
thyroid tumor (1 paper, 2010). A benign or malignant neoplasm affecting the thyroid gland. "Some internal validations emerged, such as the pairs PLAU/PLAUR, SPP1/CD44, and SPP1/ITGA9, whose ligands have been demonstrated overexpressed in thyroid tumors as well as in our in vitro model." (PMID 20877637, 2010).
triple-negative breast carcinoma (1 paper, 2020). An invasive breast carcinoma which is negative for expression of estrogen receptor (ER), progesterone receptor (PR), and human epidermal growth factor receptor 2 (HER2). "The expression of ITGA9 in triple-negative breast cancer is higher than that in other tumors, and the prognosis of patients is significantly worse." (PMID 33335550, 2020).
tumor (27 papers, 2009 to 2025). "Increased level of ITGA9 has been linked to tumor metastasis and recurrence in TNBC patients." (PMID 37469704, 2023). "Furthermore, ITGA9 protein level associated well with alpha-fetoprotein, vascular invasion, tumor thrombosis, tumor size, and TNM stage." (PMID 29951557, 2018). "Besides, ITGA9 has been strongly associated with patient outcomes in other tumour types." (PMID 36221013, 2022). "However, our analysis of the limited set of publicly available data in GEO DataSets revealed that ITGA9 mRNA expression may be linked to tumour grade, pT and to HPV status." (PMID 28102238, 2017). "In particular, the involvement of the cell adhesion and focal adhesion KEGG terms and the overlapping hub gene ITGA9 solidify the existence of a highly aggressive tumor." (PMID 39452074, 2024). "ITGA9 has been found to be an important mediator of tumor metastasis for HCC and other human tumors, serving not only as a potential prognostic factor but also as a therapeutic target specifically for suppressing metastasis in HCC." (PMID 39452074, 2024). "Both miRNA have been described as tumor suppressive in several types of cancer and are regulators of alpha-9 integrin mRNA (ITGA9) in RMS." (PMID 36033507, 2022). "ITGA9 overexpression inactivates the Rho GTPases members Rac1/RhoA and reduces FAK/Src phosphorylation, which are important in tumour angiogenesis and protease-associated metastasis." (PMID 33790909, 2021). "Changes in ITGA9 expression levels affect the interaction between tumor cells and the extracellular matrix." (PMID 34660316, 2021). "Nevertheless, our data revealed that ITGA9 not only restrains tumor growth but also suppresses tumor metastasis to prevent HCC progression." (PMID 29951557, 2018). "ITGA9 overexpression significantly inhibited cell proliferation and migration in vitro as well as tumor growth and metastasis in vivo." (PMID 29951557, 2018). "Methylation of ITGA9 gene promoter was observed in NPC tumor biopsies despite the challenge of contamination by normal stromal tissue." (PMID 26372814, 2015). "ITGA9 expression was downregulated in NPC tumor samples as compared to control nasopharyngeal epithelium." (PMID 26372814, 2015). "ITGA9 is a subunit of integrin, a cell surface receptor that plays a crucial role in promoting cell migration and regulating various cellular biological functions, including tumor cell proliferation, adhesion, and invasion." (PMID 38891754, 2024). "In addition, miR-7 and miR-324-5p regulate pro-oncogenic protein ITGA9, and overexpression of the two miRNAs reduced tumour growth in orthotopic mice tumour models." (PMID 36765536, 2023). "Knockdown of ITGA9 promotes β-catenin degradation, suggesting that integrin-α9 may interfere with the Wnt signaling pathway to influence the tumor microenvironment." (PMID 33790909, 2021). "The nanoparticle-mediated delivery of ITGA9 siRNA into tumor cells has the capacity to sharply down-regulate angiogenesis, growth and metastasis by inducing β-catenin degradation via the integrin-linked kinase (ILK)/protein kinase A (PKA)/glycogen synthase kinase 3 (GSK3) pathway." (PMID 33790909, 2021). "Similarly, the knockdown of ITGA9 abrogates primary tumor growth, angiogenesis, metastatic ability to the draining lymph node and intra-tumoral lymphangiogenesis in vivo in nude mice." (PMID 33790909, 2021). "It suggests that ITGA9 gene potentially could have important functions in tumor tissue organization and its epigenetic inactivation appears to be a major mechanism for its loss of expression in NPC." (PMID 26372814, 2015). "Taken together, this suggests that ITGA9 might be a TSG in NPC that is involved in tumor cell biology." (PMID 26372814, 2015).
tumor (continued). "Regarding pathway assignments of at least 20 HRO tumours, 10 top-ranked genes, of which 9 were lost in 3p, were linked with 7 to 45 pathways (n = 280) comprising RAF1 (45 PWs), RHOA (25 PWs), IPTR1 (22 PWs), CACNA1D, ITGA9 (8PWs), WNT7A (8 PWs) TLR9 (7PWS9, LAMB2 (7 PWs) and ARPC4 (6 PWs)." (PMID 28486536, 2017). "Ligand‒receptor analysis revealed that azvudine predominantly regulated signal transduction from tumor CD4+ T cells to other immune cells through SPP1-(ITGAV + ITGB5) and SPP1-(ITGAV + ITGB1), as well as COL1A1-(ITGA9 + ITGB1), COL1A1-CD44, and COL1A1-SDC4." (PMID 39819859, 2025). "Four interactions signaled through ITGA9 in myeloid cells, which can activate FAK, MAPK, and NFκB pathways, promoting a pro-tumor macrophage phenotype that was downregulated post-treatment." (PMID 41185627, 2025). "Analysis of the TNMplot database indicated similar expression of METTL7B and RNASE3, downregulation of ITGA9 and SOCS3, and upregulation of CLDN18 in the tumor tissues relative to the adjacent normal tissues." (PMID 37438735, 2023). "The use of CRISPR/Cas9 for the knockout of ITGA9, resulted in reduced cancer stem cell (CSC)-like properties, tumor angiogenesis, tumor growth, and metastasis by promoting β-catenin degradation in TNBC." (PMID 37469704, 2023). "The expression levels of CLDN18 (P = 4.4e-04) were significantly higher in HCC tissues compared to the normal tissues, whereas METTL7B, ITGA9, SOCS3 and RNASE3 were downregulated in the tumor tissues." (PMID 37438735, 2023). "ITGA9 has been related to cell migration, cell invasion and epithelial–mesenchymal transition (EMT) of tumour cells, all important steps for metastatic colonization." (PMID 36221013, 2022). "Tumor samples with more than 4 mm thickness exhibited significantly lower relative expression levels of ITGA3, ITGA6, ITGA9, ITGAV, and ITGB1 than samples belonging to the 2–4 mm Breslow thickness category (Mann–Whitney test, p < 0.05)." (PMID 36091936, 2022). "Mismatch repair is abolished in tumor cells that are devoid of MLH1 and carry at least one MLH1/ITGA9 fusion copy, potentially leading to global genome instability." (PMID 33500458, 2021). "These pathways were all connected to tumor growth, and the PI3K/Akt signaling pathway (eight involved genes: CCND2, CDKN1B, CSF1, EFNA3, FGFR2, FGFR3, IL2RB, and ITGA9) ranked first among upregulated pathways (Enrichment Score = 3.159187)." (PMID 30755239, 2019). "Several of those genes are known tumor suppressors that are hypermethylated in solid cancers (CACNA1G, IRF6, ITGA9, and PPP2R2C) and used as biomarkers related to adverse outcome." (PMID 30285865, 2018). "Our data suggest ITGA9, as a suppressor of HCC, prevents tumor cell migration and invasiveness through FAK/Src-Rac1/RhoA signaling." (PMID 29951557, 2018). "Of all CNA gene gains and losses, the PI3K-Akt Pathway enlisted 264 genes of which RAF1 (16 times lost), ITGA9 (15 times lost) and LAMB2 (15 times lost) were abundantly affected in HRO G1 ccRCC tumour samples." (PMID 28486536, 2017). "The methylation status of ITGA9 and WNT7A promoters in NPC tumor biopsy samples was investigated by sequencing of clones after bisulfite conversion." (PMID 26372814, 2015). "Immunostaining was performed to evaluate the expression of ITGA9 and WNT7A proteins in three cases of NPC tumor cells and adjacent control nasopharyngeal epithelium." (PMID 26372814, 2015). "Taken together, our results indicate an important role of ITGA9 in the establishment of metastasis and present RA08 as a new compound able to prevent its origin in RMS and NB models, with potential applicability in a wide range of tumour types." (PMID 36221013, 2022). "For the ITGA4, ITGA9, NID1 and NID2 genes for which XmaI-RRBS data are available, we have calculated the relative fractions of methylated and nonmethylated alleles in tumor samples, in respect to HER2 expression in tumors." (PMID 33500458, 2021).
tumor (continued). "The ITGA9 promoter showed marked differentially methylation between tumor and control tissue, whereas no differentially methylation could be detected for the WNT7A promoter." (PMID 26372814, 2015). "The ITGA9 showed a significant but extremely moderate difference between MYCN-amplified and non-MYCN-amplified tumours." (PMID 36221013, 2022). "The expression of ITGA1 and ITGA9 was correlated with the infiltration of all types immune cell in the SKCM TIME, but not tumor purity." (PMID 34660316, 2021). "In the present study ITGA9 was positively correlated with the invasion of several immune cells in SKCM TIME, but not tumor purity." (PMID 34660316, 2021). "Strong expression of ITGA9 and WNT7A was observed in membrane and cytoplasm of adjacent control nasopharyngeal epithelium cells, while weak or no expression of ITGA9 and WNT7A was observed in NPC tumor cells." (PMID 26372814, 2015).
cancer (19 papers, 2015 to 2026). A tumor composed of atypical neoplastic, often pleomorphic cells that invade other tissues. "The migration, invasion, and epithelial-mesenchymal transition (EMT) of cancer cells have all been linked to ITGA9." (PMID 37469704, 2023). "ITGA9 expression was closely associated with the pathways involved in cancer and regulation of actin cytoskeleton and focal adhesion, which was shown by KEGG pathway analysis." (PMID 29951557, 2018). "Downregulation of ITGA9 expression was observed in several cancer types that could be caused either by mutations in this gene or by hypermethylation." (PMID 27725787, 2016). "At the individual gene level, ITGA8 and ITGA9 were down-regulated in 11 out of the 15 cancers, whereas ITGAX, ITGB4, and ITGA6 were more frequently up-regulated in tumors relative to adjacent normal tissues (right)." (PMID 39436262, 2024). "In fact, LYVE1, VEGF-C and ITGA9 are among the most down-regulated genes from the low LV signature patients among all the different cancer types analyzed." (PMID 35663931, 2022). "The analysis of expression data sets revealed a significant correlation between ITGA9 and patient survival, which suggested a potential contribution of this protein to cancer progression in some specific cancer subtypes." (PMID 36221013, 2022). "ITGA9 abnormal expression was found in many cancers and was likely to correlate with higher grade cancers." (PMID 32581652, 2020). "For instance, ITGA9 is the most widely underexpressed subunit across the 17 profiled cancers, ranging from −1.41 to −5.89 fold reduction in cancer compared to normal." (PMID 30046394, 2018). "Moreover, shRNA-mediated ITGA9 downregulation was also able to impair the capability of cells to engraft and develop metastases in mice after tail-vein injection of cancer cells." (PMID 36221013, 2022). "Overview of experimental trials with therapeutic agents targeting ITGA9 in different cancers." (PMID 33790909, 2021). "Hence, there have been successive reports on the performance of α9β1 in cooperating with specific ligands in different cancers, and on the experimental effects of ITGA9-targeted therapeutic agents." (PMID 33790909, 2021). "Additionally, pan-cancer analysis showed abnormal expression and clinical outcome associations of LAMB1 and ITGA9 in multiple cancers." (PMID 32581652, 2020). "Combined with our results and previous reports, we suggest that ITGA9 in SKCM may mediate cell-cell communication between cancer cells and their microenvironment by influencing the formation of integrin and receptor complexes, and ultimately effect SKCM metastasis and progression." (PMID 34660316, 2021). "All these modifications aim to increase its stability in plasma and improve its pharmacological properties for inhibiting the ITGA9-ADAM interaction, with the ultimate aim of impairing cancer cell invasion and metastasis." (PMID 36221013, 2022). "We explored the expression and prognosis of ITGA9 and LAMB1 mRNA in different cancers based on the Oncomine database and the PrognoScan database respectively." (PMID 32581652, 2020). "One of the most remarkable families of ITGA9 interactors is the ADAM family, which has some members highly expressed in many types of cancer and can regulate cell–cell adhesion or cell-ECM interaction through its binding to adhesion molecules such as integrins and syndecans." (PMID 36221013, 2022). "Furthermore, we found that some ITGs such as ITGA3, ITGA6 ITGA11, ITGB4, ITGB6, etc. were frequently upregulated in human cancers, whereas ITGs including ITGA1, ITGA7, ITGA8, ITGA9 and ITGB3, etc. were usually downregulated." (PMID 34222028, 2021). "In cancer zone A, cancer cells primarily communicated through the COLLAGEN pathway via ligand–receptor interactions, including Col1a1-(Itga9+Itgb1), Col1a1-Cd44, Col1a2-(Itga9+Itgb1), and Col1a2-Cd44, with Col1a2-(Itga9+Itgb1)/Cd44 showing the strongest interaction strength." (PMID 40723284, 2025).
infection (1 paper, 2016). The state of being infected such as from the introduction of a foreign agent such as serum, vaccine, antigenic substance or organism. "Based on the observation that forced expression of Itga9 and kindlin stimulates regenerative growth of axons also in an otherwise inhibitory environment, the authors have examined the distribution of a9-integrin expressed in distinct neuronal classes via infection with Lenti- or adenoviruses." (PMID 27570822, 2016). "The salient finding of the study is that Itga9 does not distribute into certain types of CNS axons after infection." (PMID 27570822, 2016).
ITGA9 also shares sentences with these, for which no sentence is quoted: central nervous system cancer (2 papers); experimental autoimmune encephalomyelitis (2); oral squamous cell carcinoma (2); prostate carcinoma (2); autoimmune disease (1); B cell lymphoma (1); cardiovascular diseases (1); dyskeratosis congenita (1); esophagus cancer (1); gastric cancer (1); giant cell glioblastoma (1); glioma (1); head and neck squamous cell carcinoma (1); heart failure (1); hypertrophic cardiomyopathy (1); kidney diseases (1); leiomyosarcoma (1); leukoplakia (1); lichen planus (1); lung adenocarcinoma (1); lung squamous cell carcinoma (1); mucinous adenocarcinoma (1); nasopharyngeal carcinoma (1); neuroblastoma (1); neuropathic pain (1); prostate tumors (1); pulmonary emphysema (1); pulmonary fibrosis (1); pulmonary hypertension (1); sarcoidosis (1).
A further 4 diseases each share a sentence with ITGA9 in 1 paper.